THOC6 (THO complex subunit 6)
Description:
Component of the THO subcomplex of the TREX complex which is thought to couple mRNA transcription, processing and nuclear export, and which specifically associates with spliced mRNA and not with unspliced pre-mRNA. Plays a key structural role in the oligomerization of the THO-DDX39B complex. TREX is recruited to spliced mRNAs by a transcription-independent mechanism, binds to mRNA upstream of the exon-junction complex (EJC) and is recruited in a splicing- and cap-dependent manner to a region near the 5' end of the mRNA where it functions in mRNA export to the cytoplasm via the TAP/NXF1 pathway. Plays a role in apoptosis negative control involved in brain development. (Microbial infection) The TREX complex is essential for the export of Kaposi's sarcoma-associated herpesvirus (KSHV) intronless mRNAs and infectious virus production.
Synonyms: fSAP35; WDR58; MGC2655; MMRFCGU
Tractability: PROTAC: ubiquitination databases record sites on it; its protein half-life has been measured.
Gene: Protein-coding gene on chromosome 16 (3,022,541 to 3,027,755, forward strand). Ensembl gene ENSG00000131652.
Subcellular location: Nucleus; Nucleus speckle
Subcellular location (Human Protein Atlas): Nuclear speckles; Nucleoplasm
Pathways (Reactome):
Metabolism of RNA: Transport of Mature mRNA derived from an Intron-Containing Transcript; mRNA 3'-end processing
Gene Ontology:
Biological process: central nervous system development; mRNA export from nucleus
Cellular component: chromosome, telomeric region; nuclear speck; nucleoplasm; nucleus; THO complex; THO complex part of transcription export complex; transcription export complex
Genetic constraint (gnomAD): Loss-of-function variants: 39 observed, 58.43 expected, observed/expected ratio (o/e) 0.67, 90% interval 0.52 to 0.87. The upper end of that interval is the gene's LOEUF score, 0.87, which puts it in group 3 of 6, group 1 being the genes least tolerant of losing a copy. Missense variants: 482 observed, 464.57 expected, observed/expected ratio (o/e) 1.04, 90% interval 0.96 to 1.12. Synonymous variants: 192 observed, 185.05 expected, observed/expected ratio (o/e) 1.04, 90% interval 0.92 to 1.17.
Gene-disease validity (ClinGen):
ClinGen rates the evidence that THOC6 causes each of these diseases.
THOC6-related developmental delay-microcephaly-facial dysmorphism syndrome (autosomal recessive): Definitive.
Homologues: Orthologues: chimpanzee THOC6 (99% identical), dog THOC6 (97% identical), guinea pig THOC6 (96% identical), pig THOC6 (96% identical), rat Thoc6 (95% identical), mouse Thoc6 (95% identical), macaque THOC6 (89% identical), tropical clawed frog thoc6 (59% identical), zebrafish thoc6 (56% identical).
Diseases named in the same sentence as THOC6 in open-access papers:
THOC6 is named in the same sentence as 21 diseases in open-access papers, as found by Europe PMC text mining. Sharing a sentence is not in itself a finding about the gene and the disease. The quoted sentences say what the papers report.
Beaulieu-Boycott-Innes syndrome (8 papers, 2020 to 2025). "Beaulieu–Boycott–Innes syndrome (BBIS) is a rare autosomal recessive neurodevelopmental disorder caused by THOC6 gene mutations." (PMID 40760536, 2025). "Patients identified in this review with Beaulieu-Boycott-Innes syndrome and THOC6 mutations have been shown to develop HC, suggesting a role for mRNA export regulation in association with HC phenotypes." (PMID 38439105, 2024). "The first (case 26) was compound heterozygous for four known missense variants (of which three on the maternal allele that have been described as a pathogenic haplotype) in THOC6, causing Beaulieu-Boycott-Innes syndrome (OMIM# 613680)." (PMID 36900003, 2023). "The region is associated with familial Mediterranean fever and the Beaulieu‐Boycott‐Innes syndrome caused by THOC6 mutation, which causes DD, ID, and dysmorphic facial features." (PMID 37013606, 2023). "Beaulieu-Boycott-Innes syndrome (BBIS) is a rare autosomal recessive neurodevelopmental disorder associated with the THO complex 6 gene (THOC6), and is clinically characterized by developmental delay, moderate to severe intellectual disability (ID) and subtle dysmorphic facial features." (PMID 32282736, 2020). "It should be noted that the deletions in P1 and P3 extend further in the proximal direction and include THOC6 (MIM #613680, Beaulieu-Boycott-Innes Syndrome) and CLDN9 (deafness, autosomal recessive 116, provisional, #619093)." (PMID 40225164, 2023).
Intellectual disability (4 papers, 2013 to 2025). "THOC6 mutations have also been associated with intellectual disability, consistent with its high expression levels in the developing zebrafish brain." (PMID 27679854, 2016). "Our findings associate a missense mutation in THOC6 with intellectual disability, suggesting the THO/TREX complex plays an important role in neurodevelopment." (PMID 23621916, 2013). "Furthermore, a homozygous mutation in a conserved region of THOC6 is the likely cause of a disease with clinical features such as intellectual disability, brain malformation and renal and heart defects." (PMID 27679854, 2016). "Given that THOC6 is a member of the THO complex, mutations in other complex members may explain a portion of intellectual disability." (PMID 23621916, 2013).
Intellectual Disability Syndrome (3 papers, 2023 to 2025). "Elizabeth A. Werren and colleagues used both in vivo (mouse) and in vitro (human stem cell-derived) models to expand the known spectrum of THOC6 variants linked to THOC6 intellectual disability syndrome." (PMID 40760536, 2025). "THOC6 variants are the genetic basis of autosomal recessive THOC6 Intellectual Disability Syndrome (TIDS)." (PMID 38388531, 2024). "Analysis of pathogenic THOC6 variants differentiate the conserved mRNA export functions of TREX dimers and RNA processing functions of TREX tetramers underlying THOC6 Intellectual Disability Syndrome." (PMID 38388531, 2024). "THOC6 is the genetic basis of autosomal recessive THOC6 Intellectual Disability Syndrome (TIDS)." (PMID 37720017, 2023).
breast carcinoma (1 paper, 2011). "We evaluated the expression of the components of the human THO complex, THOC1, THOC2, THOC3, THOC5, THOC6 and THOC7, as well as the expression levels of UAP56 and ALY in breast cancer cell lines." (PMID 21329510, 2011).
cryptorchidism (1 paper, 2025). The failure of one or both testes of a male fetus to descend from the abdomen into the scrotum during the late part of pregnancy. "Recent studies have linked mutations in the THOC6 gene, which is crucial for RNA processing and mRNA export, to clinical features such as cryptorchidism and hypogonadism." (PMID 40760536, 2025).
pneumonia (1 paper, 2020). An acute, acute and chronic, or chronic inflammation focally or diffusely affecting the lung parenchyma, caused by an infection in one or both of the lungs (by bacteria, viruses, fungi, or mycoplasma.). "This study identifies two novel compound heterozygous variants of the THOC6 gene in a Chinese patient, who expressed ID, subtle facial features, short stature, cardiac abnormality, recurrent pneumonia, and mesenteric cysts." (PMID 32282736, 2020).
Primary microcephaly (1 paper, 2024). Head circumference below 2 standard deviations below the mean for age and gender at birth. "Primary microcephaly is a clinical feature of TIDS, attributed to developmental defects in hNPCs during corticogenesis, making this an important cell type to investigate THOC6 pathogenesis." (PMID 38388531, 2024).
prostate carcinoma (1 paper, 2021). A carcinoma that arises from epithelial cells of the prostate gland. "THOC1, THOC2, THOC5 and THOC6, members of the THO subcomplex of TREX which participates in mRNA processing and transport of RNPs from nucleus to cytoplasm, are present in HMGB1 immunoprecipitates from ovary and prostate cancer cells." (PMID 34572914, 2021).
Tetralogy of Fallot (1 paper, 2023). A congenital cardiac malformation comprising pulmonary stenosis, overriding aorta, ventricular septum defect, and right ventricular hypertrophy. "The fetus with the THOC6 variants displayed Tetralogy of Fallot, cerebellar hypoplasia, mild ventriculomegaly and hypospadias." (PMID 36900003, 2023).
cancer (3 papers, 2011 to 2024). A tumor composed of atypical neoplastic, often pleomorphic cells that invade other tissues. "Multiple TREX mRNA export complex subunits (e.g., THOC1, THOC2, THOC5, THOC6, THOC7) have now been implicated in neurodevelopmental disorders (NDDs), neurodegeneration and cancer." (PMID 32116545, 2020). "LncBCl2L11 prevented the binding of THOC6 and THOC5 and causes the degradation of THOC5, thus promoting the accumulation of acylcarnitines in GBC cells, leading to the malignant progression of cancer cells." (PMID 38519939, 2024).
tumor (1 paper, 2024). "The reasons supporting our hypothesis are as follows: RNA pulldown assay confirmed the interaction between lncBCL2L11 and THOC6 in tumor cells." (PMID 38519939, 2024).
THOC6 also shares sentences with these, for which no sentence is quoted: neurodevelopmental disorder (2 papers); autosomal recessive intellectual disability (1); congenital malformations (1); deafness (1); developmental delay (1); familial Mediterranean fever (1); hypogonadism (1); Kabuki syndrome (1); periodontitis (1); Stickler syndrome (1).